KLC4 (kinesin light chain 4)
Description:
Kinesin is a microtubule-associated force-producing protein that may play a role in organelle transport. The light chain may function in coupling of cargo to the heavy chain or in the modulation of its ATPase activity (By similarity).
Synonyms: KNSL8; bA387M24.3; CONDRHN
Tractability: PROTAC: ubiquitination databases record sites on it; its protein half-life has been measured.
Gene: Protein-coding gene on chromosome 6 (43,040,777 to 43,075,099, forward strand). Ensembl gene ENSG00000137171.
Subcellular location: Cytoplasm, cytoskeleton
Subcellular location (Human Protein Atlas): Mitochondria; Cytosol
Pathways (Reactome):
Hemostasis: Kinesins
Immune System: MHC class II antigen presentation
Signal Transduction: RHO GTPases activate KTN1
Vesicle-mediated transport: COPI-dependent Golgi-to-ER retrograde traffic
Gene Ontology:
Molecular function: protein binding; kinesin binding
Biological process: microtubule-based movement
Cellular component: cytoplasm; cytoskeleton; kinesin complex
Genetic constraint (gnomAD): Loss-of-function variants: 45 observed, 72.87 expected, observed/expected ratio (o/e) 0.62, 90% interval 0.49 to 0.79. The upper end of that interval is the gene's LOEUF score, 0.79, which puts it in group 3 of 6, group 1 being the genes least tolerant of losing a copy. Missense variants: 645 observed, 798.45 expected, observed/expected ratio (o/e) 0.81, 90% interval 0.76 to 0.86. Synonymous variants: 268 observed, 323.02 expected, observed/expected ratio (o/e) 0.83, 90% interval 0.75 to 0.92.
Homologues: Orthologues: chimpanzee KLC4 (100% identical), macaque KLC4 (99% identical), rabbit KLC4 (97% identical), guinea pig KLC4 (97% identical), rat Klc4 (96% identical), dog KLC4 (95% identical), mouse Klc4 (94% identical), pig KLC4 (94% identical), tropical clawed frog klc4 (70% identical), zebrafish klc3 (54% identical), zebrafish klc4 (18% identical). Paralogues in human: KLC2 (70% identical), KLC1 (68% identical), KLC3 (51% identical), NPHP3 (29% identical), APPBP2 (19% identical).
Diseases named in the same sentence as KLC4 in open-access papers:
KLC4 is named in the same sentence as 17 diseases in open-access papers, as found by Europe PMC text mining. Sharing a sentence is not in itself a finding about the gene and the disease. The quoted sentences say what the papers report.
cervical cancer (3 papers, 2018 to 2022). A primary or metastatic malignant neoplasm involving the cervix. "Next, we confirmed the correlation between KLC4 expression and cervical cancer severity with the Oncomine database, a human genetic data set analysis tool." (PMID 29717133, 2018). "In addition, the correlation between KLC4 and CHEK1, CHEK2 was investigated in both lung cancer and cervical cancer using RNA-sequencing data from publicly available microarray datasets." (PMID 32457423, 2020). "Moreover, SETD3 downregulates the expression of kinesin light chain 4 (KLC4), which could improve the radiosensitivity of cervical cancer cells." (PMID 35912180, 2022).
lung carcinoma (3 papers, 2018 to 2021). "Altogether, these data indicated that KLC4 was overexpressed in lung cancer, and its overexpression may be associated with radioresistance." (PMID 29717133, 2018). "The purpose of the study was to clarify whether KLC4 is a radioresistance biomarker in lung cancer cells and to characterize the underlying mechanisms." (PMID 29717133, 2018). "Targeting KLC4 by siRNAs in lung cancer cell lines.Generation of mouse xenograft tumors with lung cancer cells lacking KLC4." (PMID 34900673, 2021). "We first evaluated the anticancer drug resistance of the lung cancer cell lines, H460 with lower KLC4 expression, and R-H460 and A549 with higher KLC4 expression than that of H460 cells." (PMID 32457423, 2020). "Inhibition of KLC4 expression in the three types of lung cancer cell lines increased the expression level of γ-H2AX." (PMID 32457423, 2020). "KLC4 protein levels in lung cancer cells correlated with the degree of chemoresistance to cisplatin treatment." (PMID 32457423, 2020). "Western blotting further showed that KLC4 protein levels in human lung cancer cell lines (H460, R-H460, and A549 cells) correlated with the tendency of chemoresistance." (PMID 32457423, 2020). "Compared with that observed with KLC4 siRNA treatment alone, knockdown of KLC4 in combination with cisplatin also increased lung cancer cell death, as was evident from the evaluation of apoptosis using flow cytometry." (PMID 32457423, 2020). "Colony formation decreased as the radiation dose increased in KLC4-knockdown lung cancer cells, demonstrating an essential role for KLC4 in radioresistance." (PMID 29717133, 2018). "The results showed that the KLC4 level was correlated with radioresistant tendency in the human lung cancer cell lines." (PMID 29717133, 2018). "Consistent with the results of lung cancer lines, the KLC4 protein expression was higher in radioresistant SiHa cells than HeLa cells." (PMID 29717133, 2018). "Key evidence in the present study included the overexpression of KLC4 in several lung cancer cells, particularly in lung cancer patients, as well as KLC4 depletion-induced apoptosis following radiation treatment in R-H460 cells and the in vivo model." (PMID 29717133, 2018). "Fluorescence-activated cell sorting (FACS) analysis showed that apoptosis rates and cleaved poly (ADP-ribose) polymerase (PARP) and cleaved caspase-3 levels in KLC4-knockdown lung cancer cells were significantly increased compared with those in control cells." (PMID 29717133, 2018). "Collectively, these results show that KLC4 has an essential role in radioresistance of lung cancer cells." (PMID 29717133, 2018). "To determine the level of KLC4 in lung cancer patients, we first investigated KLC4 expression in paired clinical lung specimens." (PMID 29717133, 2018). "We showed that siKLC4-treated cells exhibit an increased level of mitochondrial dysfunction through calcium uptake, suggesting that mitochondria participate in apoptosis involving KLC4 in lung cancer cells." (PMID 29717133, 2018). "Because KLC4 is overexpressed in radioresistant lung cancer cell lines and tissues from lung cancer patients, it could be favoring mitochondrial homeostasis and the survival of tumor cells." (PMID 34900673, 2021). "To investigate whether cisplatin as a DNA damage inducer altered double strand break (DSB) repair, we attempted to validate DDR according to KLC4 expression in the lung cancer cell lines." (PMID 32457423, 2020). "In addition, investigations on the effects of KLC4 inhibition on normal cells are required to minimize any potential complications of its inhibition in clinical application for lung cancer treatment." (PMID 32457423, 2020). "To investigate the mechanism underlying this resistance, we examined the potential link between kinesin light chain 4 (KLC4), which we have previously reported to be associated with radioresistance in NSCLC, and sensitivity to chemotherapy in human lung cancer cell lines." (PMID 32457423, 2020).
lung carcinoma (continued). "We first investigated whether KLC4 expression and sensitivity to chemotherapy or radioresistance in lung cancer cell lines treated with cisplatin or other common chemotherapy drugs were related." (PMID 32457423, 2020). "Expression of KLC4 was also related to the sensitivity of lung cancer cells to chemotherapy." (PMID 32457423, 2020). "In addition, KLC4 mRNA and protein levels in human lung cancer cell lines (H1299, A549, H460 and R-H460) were analyzed by RT-PCR and Western blots." (PMID 29717133, 2018). "Moreover, in paired clinical specimens of lung cancer patients, KLC4 expression was significantly higher in tumor tissues than in paired adjacent normal tissues." (PMID 29717133, 2018). "Thus, we focused on the role of KLC4 in cancers, especially lung cancer, after RT for the first time." (PMID 29717133, 2018). "Thus, we investigated KLC4 function in lung cancer cells and radioresistant R-H460 cells by analyzing alterations in radiosensitivity after gene knockdown with siRNA and by evaluating cellular phenotypes and xenograft tumor growth." (PMID 29717133, 2018). "Depletion of KLC4 overcomes the radioresistance of in vitro and in vivo human lung cancer models, and this may significantly enhance the consequence of lung cancer patients, considerably those who exhibit resistance to RT." (PMID 29717133, 2018). "Consistently, transfection of siKLC4, combined with cisplatin or etoposide, markedly enhanced the accumulation of γ-H2AX at the protein level, indicating that KLC4 depletion may considerably increase the genotoxic effect of cisplatin and etoposide in aggravating DNA damage in lung cancer cells." (PMID 32457423, 2020). "Thus, inhibiting KLC4 may be a new strategy for overcoming chemoresistance in lung cancer cells and simultaneously enhancing the effects of chemotherapy in patients with lung cancer." (PMID 32457423, 2020). "However, the regulatory mechanism linking KLC4 expression and sensitivity to chemotherapy or radioresistance in lung cancer remains unclear." (PMID 32457423, 2020). "Our results indicate a novel link between the KLC4 and CHK2 pathways regulating DNA damage response in chemoresistance, and highlight KLC4 as a candidate for developing lung cancer-specific drugs and customized targeted molecular therapy." (PMID 32457423, 2020). "Overall, these results indicated that KLC4 may prevent DNA damage repair and increase DNA damage by inhibiting CHK1/2 in lung cancer cells." (PMID 32457423, 2020). "The expression of endogenous KLC4 between human lung cancer tissues and paired adjacent non-tumor tissues was analyzed by immunohistochemical staining." (PMID 29717133, 2018).
Anxiety (2 papers, 2021 to 2022). Intense feelings of nervousness, tension, or panic often arise in response to interpersonal stresses. "Behavioral analysis also showed that klc4 mutant adults exhibit increased anxiety-like behavior, indicating roles for KLC4 in adult circuit function and identifying KLC4 as a novel gene associated with anxiety behavior." (PMID 36222498, 2022). "In addition, because KLC4 and other kinesin-1 subunits have been implicated in neurodegenerative diseases, we sought to determine whether the anxiety-like behavior worsened with age." (PMID 36222498, 2022). "Our finding that klc4uw314 mutant adults show freezing and reduced exploration in the novel tank assay implicates KLC4 in the circuits that regulate stress response and that are affected in anxiety and depression disorders." (PMID 36222498, 2022). "Finally, we find that klc4 mutant larva are hypersensitive to touch and adults show anxiety-like behavior in a novel tank test, implicating klc4 as a new gene involved in stress response circuits." (PMID 36222498, 2022).
hereditary spastic paraplegia (2 papers, 2022 to 2023). Hereditary spastic paraplegias (HSP) comprise a genetically and clinically heterogeneous group of neurodegenerative disorders characterized by progressive spasticity and hyperreflexia of the lower limbs. "Mutation of KLC4 in humans causes a type of hereditary spastic paraplegia (HSP) that manifests in early childhood, indicating essential developmental functions." (PMID 36222498, 2022).
breast carcinoma (1 paper, 2020). "Also, to analyze the gene expression of additional molecules regulated by SETD310,22,29–32 that could potentially explain the differences between the prognostic impact on diverse breast cancer subtypes, we also quantified MMP-2, KLC4, iNOS and eNOS mRNA levels in MCF-7 and MDA-MB-231 cells." (PMID 32042016, 2020).
colorectal cancer (1 paper, 2020). A primary or metastatic malignant neoplasm that affects the colon or rectum. "Kaplan–Meier analysis showed that high KLC4 and low CHEK2 expression resulted in significantly lower survival rates for patients with lung and colorectal cancer." (PMID 32457423, 2020).
epithelial ovarian cancer (1 paper, 2023). "Moreover, TNPO1, ACLY, NME1, FLOT1, and KLC4 are proteins already known to be involved in epithelial ovarian cancer." (PMID 37775701, 2023).
Myelopathy (1 paper, 2023). Myelopathy is an descriptive term, referring to pathology leading to a neurologic deficit related to the spinal cord. "A male individual with the clinical KLC4 variant presented to the Undiagnosed Diseases Network (UDN) with slowly progressive myelopathy and neuropathy since ∼50 years of age." (PMID 37565267, 2023).
tumor (5 papers, 2018 to 2024). "Loss of Kinesin light chain 4 (KLC4) promotes apoptotic cell death and a decreased tumor growth in a mouse xenograft model." (PMID 34900673, 2021). "The strongest tumor growth inhibitory effect was observed in the KLC4 siRNA plus IR group, which had a tumor inhibition rate of 66.3%." (PMID 29717133, 2018). "KLC4 siRNA was injected into the subcutaneous tumors in nude mice, triggered by R-H460 cells and tumor volume was measured thrice a week." (PMID 29717133, 2018). "Upon termination of the experiment, the average tumor volume was 1073.5, 705.4, 555.1 and 292.9 mm3 for the control siRNA, KLC4 siRNA, IR, and plus IR groups, respectively." (PMID 29717133, 2018). "We noticed a significant difference observing the lightest tumor weight in KLC4 siRNA plus IR group." (PMID 29717133, 2018). "These events included the activation of PARP and caspase-3, which ultimately promote tumor cell apoptosis induced by KLC4 knockdown." (PMID 29717133, 2018). "Seven potential tumor antigens, [SREBF1, LUC7L3, LAMA5, PCGF3, HNRNPH1, KLC4, and OFD1], which were associated with nonsense-mediated mRNA decay factor expression, overall survival, and infiltration of APCs and would thus induce a potent anti-tumor T-cell response." (PMID 39399167, 2024). "Moreover, KLC4 is a light chain isoform of kinesin that is observed at higher levels in tumor tissue than in healthy tissue." (PMID 36467412, 2022). "Importantly, KLC4 silencing suppressed tumor growth in an in vivo xenograft model, accompanied by increased apoptosis." (PMID 29717133, 2018). "In our study, we identified a series of potential tumor antigens, including SREBF1, LUC7L3, LAMA5, PCGF3, HNRNPH1, KLC4, and OFD1, by systematically analyzing alternative splicing and mutation of genes in patients with HNSCC." (PMID 36467412, 2022). "Among the 27 cases, positive KLC4 expression was observed in tumor tissues compared with the paired adjacent non-tumor tissues (P < 0.001)." (PMID 29717133, 2018). "However, until now, the expression pattern of KLC4 in tumor tissue, function of KLC4 in malignant phenotypes, and potential implications of KLC4 expression have not been identified in the context of radioresistance." (PMID 29717133, 2018).
cancer (3 papers, 2018 to 2022). A tumor composed of atypical neoplastic, often pleomorphic cells that invade other tissues. "In this regard, the present study provides new insights into the crosstalk between the CHK2 pathway and the KLC4-regulated apoptotic pathway, which contributes to our understanding of the mechanism underlying the development of drug resistance in cancer cells." (PMID 32457423, 2020). "Previously, we had reported that KLC4 depletion induces apoptosis of radioresistant cancer cells via mitochondrial dysfunction due to calcium ion influx." (PMID 32457423, 2020). "In this study, we further investigated the function of KLC4 following small interfering RNA (siRNA) gene knockdown and cellular and xenograft mouse-based analyses in cancer cells." (PMID 29717133, 2018). "We first showed that when highly expressed KLC4 in cancer is knocked down, the major evidence for cell death is related to mitochondrial dysfunction." (PMID 29717133, 2018). "Given that resistance to anticancer drugs, as well as radiation resistance, is a problem observed in many cancer patients, we aimed to determine whether KLC4 affected anticancer resistance in this study." (PMID 32457423, 2020). "Our results showed that up- or downregulation of KLC4 can affect cancer cell proliferation." (PMID 32457423, 2020). "However, to the best of our knowledge, this is the first study to focus on the biological chemoresistance function of KLC4 in cancer." (PMID 32457423, 2020). "Based on our findings, KLC4 may represent a novel and more effective approach for cancer treatment, especially for those patients who exhibit resistance to RT, and thus, KIF-targeted therapy may be a promising anticancer strategy." (PMID 29717133, 2018). "In addition, the biological phenotypes related to radiation in cancer therapy have not been identified yet; thus, we investigated the characteristics of KLC4 in cancer." (PMID 29717133, 2018).
neuromuscular disease (1 paper, 2023). "The success of the humanized KLC4 C. elegans line described here suggests that this approach could be feasible for modeling other neuromuscular diseases associated with LINC complex dysfunction." (PMID 37565267, 2023).
KLC4 also shares sentences with these, for which no sentence is quoted: cardiomyopathy (1 paper); depression disorders (1); left ventricular hypertrophy (1); neurodegenerative disease (1); neuropathy (1); non-small cell lung carcinoma (1).